NEDD4 (NEDD4 E3 ubiquitin protein ligase)
Diseases named in the same sentence as NEDD4 in open-access papers (continued):
Sharing a sentence is not in itself a finding about the gene and the disease.
keloid (continued). "Similarly, NEDD4 could participate in keloid formation by enhancing the proliferation and invasiveness of fibroblasts and up-regulating the expression of type I collagen." (PMID 37644565, 2023). "In keloids, PTEN expression is markedly reduced, and its inverse correlation with NEDD4-1 highlights post-translational regulation as a key driver of aberrant fibroblast growth and tissue remodeling." (PMID 41424791, 2025).
Parkinson disease (11 papers, 2014 to 2026). A progressive degenerative disorder of the central nervous system characterized by loss of dopamine producing neurons in the substantia nigra and the presence of Lewy bodies in the substantia nigra and locus coeruleus. "The potential of Nedd4 modulation offers a novel approach to address the underlying molecular mechanisms contributing to Parkinsons disease, bringing new prospects for developing targeted therapies." (PMID 38960968, 2024). "Also, the findings emphasize the therapeutic potential of targeting Nedd4 to address α-synuclein-associated trafficking defects in Parkinsons disease." (PMID 38960968, 2024). "Fly and rat models of Parkinson’s, featuring ectopic α-synuclein expression, show suppression and enhancement of α-synuclein pathological effects with NEDD4 overexpression or knockdown, respectively." (PMID 41498748, 2026). "Experimental evidence from Drosophila and animal models utilized in Parkinsons research studies suggests that Nedd4-mediated degradation acts protectively against alpha-synuclein-induced toxicity." (PMID 38960968, 2024). "Nedd4, a HECT-domain E3 ligase enzyme, is crucial in the intracellular ubiquitination process and protective mechanisms associated with Parkinsons disease (PD)." (PMID 38960968, 2024). "The benzimidazole NAB2 has demonstrated efficacy in rescuing α-synuclein-associated trafficking defects, particularly in the context of early onset Parkinsons disease, and acts in a Nedd4-dependent manner." (PMID 38960968, 2024). "Targeting Nedd4-mediated ubiquitination of α-synuclein is a promising therapeutic strategy for mitigating Parkinsons disease and other α-synucleinopathies." (PMID 38960968, 2024). "The NEDD4 protein involved in the pathological process of neurodegeneration diseases, such as Parkinson's, has been found both in animal models and postmortem studies." (PMID 33897484, 2021). "Upregulation of NEDD4-1 has been noted in neurodegenerative diseases such as AD, Parkinson’s disease, amyotrophic lateral sclerosis, and Huntington’s disease." (PMID 34867205, 2021). "Nedd4–2 directly targets glutamate transporter and inhibits glutamate uptake in a Parkinson’s disease model." (PMID 31704983, 2019). "Strangely enough, NEDD4 was also reported to be the E3 ligase of α-syn in Parkinsonism via the endosomal–lysosomal pathway." (PMID 26503960, 2016). "Nedd4 is a HECT domain-containing E3 ubiquitin ligase with a wide range of protein targets, the dysregulation of which has been implicated in myriad pathologies, including cancer and Parkinson's disease." (PMID 37749144, 2023). "Importantly, in the CNS, up-regulation of NEDD4 has been noted in several neurodegenerative diseases such as Alzheimer’s, Parkinson’s disease, and Huntington’s disease." (PMID 36980307, 2023). "NEDD4-1 protein was detected in the dopaminergic system in neuromelanin-positive neurons and in reactive glia cells in the substantia nigra and locus coeruleus of Parkinson’s disease and in Lewy body dementia patient brains containing Lewy bodies." (PMID 35328067, 2022). "Here we asked whether Nedd4-mediated degradation protects against α-synuclein-induced toxicity in the Drosophila and rodent models of Parkinson's disease." (PMID 24388974, 2014).
glioma (10 papers, 2013 to 2023). A benign or malignant brain and spinal cord tumor that arises from glial cells (astrocytes, oligodendrocytes, ependymal cells). "Firstly, we examined whether NEDD4-1 has a role in cell migration and invasion using gain-of and loss-of function approach in glioma cells." (PMID 24340059, 2013). "Another study in U251 and U87 demonstrated that NEDD4 regulates glioma cell motility and invasion via the NEDD4/Rap2a pathway." (PMID 36293239, 2022). "Another similar study in GBM revealed that glioma-linked oncogenic lncRNA LINC01198 promotes proliferation of gliomas and temozolomide resistance by acting as a scaffold and enlisting NEDD4 enzymes to attack certain proteins such as PTEN." (PMID 36293239, 2022). "Another study revealed that curcumin can reduce the expression of NEDD4, pAkt, and Notch1, which leads to the inhibition of cell growth and apoptosis and reduction in invasion and migration of glioma cells." (PMID 36293239, 2022). "For example, in glioma cells, curcumin, a diarylheptanoid ingredient found in Curcuma longa plants, decreased proliferation, invasion, and migration by suppressing NEDD4." (PMID 36293239, 2022). "In U251 glioma cells, it was reported that NEDD4 overexpression enhanced the cell invasion and migration due to ubiquitination and degradation of cyclic nucleotide ras guanine nucleotide exchange factor (CNrasGEF)." (PMID 36293239, 2022). "NEDD4 was shown to promote cell motility and invasion of malignant U251 glioma cells in vitro by ubiquitinating CNrasGEF." (PMID 36293239, 2022). "Downregulated CNrasGEF promotes cell migration and invasion, and facilitates the effect of NEDD4-induced cell motility, which indicates that NEDD4 exerts an oncogenic function in glioma cell motility through ubiquitination of CNrasGEF." (PMID 33767993, 2021). "In conclusion, our results indicate that the glioma-associated lncRNA LINC01198 is an oncogenic lncRNA that promotes glioma progression by serving as a scaffold and recruiting NEDD4-1 enzymes to target specific proteins, such as PTEN." (PMID 31469661, 2019). "Collectively, these observations suggest that LINC01198 enhances AKT activity through NEDD4-1-induced PTEN ubiquitin degradation in glioma cells." (PMID 31469661, 2019). "Zhang found that NEDD4-1 promoted but CNrasGEF inhibited the migration and invasion of glioma cells." (PMID 31787758, 2019). "In this study we investigated the function and mechanism of NEDD4-1 in glioma cell migration and invasion in vitro." (PMID 24340059, 2013). "We found that NEDD4-1 promoted the glioma cell migration and invasion via triggering cyclic nucleotide Ras guanine nucleotide exchange factors (CNrasGEF) ubiquitination and degradation." (PMID 24340059, 2013). "In this study, we show that NEDD4-1 plays a key regulatory effect in the migratory and aggressive behavior of glioma via regulating ubiquitination of CNrasGEF." (PMID 24340059, 2013). "Our results above demonstrated that NEDD4-1 promoted the migration and invasion of the glioma U251 and U87 cells and CNrasGEF ubiquitination and degradation." (PMID 24340059, 2013). "Combined with the in vitro results, the result of glioma tissues indicated post-translationally modification effect of NEDD4-1 on CNrasGEF." (PMID 24340059, 2013). "Third, CNrasGEF downregulation promoted the migration and invasion of human glioma cells, CNrasGEF overexpression inhibited them, which is contrary to the effect of NEDD4-1." (PMID 24340059, 2013). "As migration and invasion have close inter-communication and NEDD4-1 manipulation affected the migration of human glioma cells, we next examined the role of NEDD4-1 in invasion of glioma cells using matrigel precoated transwell chambers." (PMID 24340059, 2013). "The NEDD4-1 staining scores of glioma samples were 10.35% to low (0-+), 31.03% (++) moderate and 58.62% strong positive (+++) (P<0.01)." (PMID 24340059, 2013).
glioma (continued). "In this work, we found that NEDD4-1 promotes the glioma cell migration and invasion, suggesting that NEDD4-1 exerts a regulatory effect upon the migration and aggressive behavior of glioma." (PMID 24340059, 2013). "In addition, human glioma cells showed suppression of invasion and migration when NEDD4 was downregulated, but overexpression of NEDD4 reversed these effects." (PMID 36293239, 2022). "Curcumin, in the dose range of 10–20 μM, suppressed E3 ubiquitin–protein ligase NEDD4 (Neural precursor cell Expressed Developmentally Downregulated protein 4) which is overexpressed in gliomas, leading to inhibition of cell proliferation, apoptosis, cell migration, and invasion." (PMID 33118056, 2021). "Overexpression of LINC01198 by enhancing the NEDD4-1-dependent repression of PTEN could promote glioma cell proliferation and resistance to TMZ." (PMID 34178658, 2021). "We thus evaluated the effect of LINC01198 on NEDD4-1-induced PTEN inhibition in glioma cells." (PMID 31469661, 2019). "NEDD4-1 ubiquitinated CNrasGEF and post-translationally modified CNrasGEF in glioma tissues." (PMID 31787758, 2019). "Furthermore, the effect of NEDD4-1 on glioma cell migration and invasion was also observed in U87 glioma cells through either wound-healing assay or transwell invasion assay." (PMID 24340059, 2013). "On the contrary, higher immunoactivity of NEDD4-1 was detected in human gliomas." (PMID 24340059, 2013). "Here we report that NEDD4-1 regulates migration and invasion of malignant glioma cells via triggering ubiquitination of cyclic nucleotide Ras guanine nucleotide exchange factor (CNrasGEF) using cultured glioma cells." (PMID 24340059, 2013). "Therefore, we examined the mRNA and protein levels of NEDD4-1 and CNrasGEF in glioma tissues by RT-PCR and western blotting." (PMID 24340059, 2013). "We found that NEDD4-1 was highly expressed both at mRNA and protein levels in human glioma tissues, suggesting that NEDD4-1 might play some roles in glioma progression." (PMID 24340059, 2013). "It is thus possible that NEDD4-1-CNrasGEFsignaling might be a novel potential therapeutic target for human glioma." (PMID 24340059, 2013). "To examine whether the migration effect of NEDD4-1 was the secondary effect of proliferation, we also checked the effect of NEDD4-1 on glioma cell proliferation and apoptosis." (PMID 24340059, 2013). "Next, we examined whether CNrasGEF interacts with NEDD4-1 in glioma cells using co-immunoprecipitation assays." (PMID 24340059, 2013). "Finally, we studied the clinical relevance of NEDD4-1 and CNrasGEF, and their relationship in clinical glioma samples." (PMID 24340059, 2013). "In addition, the expression level of NEDD4-1 protein significantly correlated with the malignancy grade of the glioma." (PMID 24340059, 2013). "We found that shNEDD4-1 cannot down-regulate the large amount of exogenous NEDD4-1 anymore and the exogenous NEDD4-1 can abolish the inhibition effect of shNEDD4-1 on glioma cell migration both in U251 and U87, suggesting that the effect of shNEDD4-1 on cell migration was specific (*P<0.01)." (PMID 24340059, 2013). "Furthermore, deletion of NEDD4 sensitized glioma cells to curcumin." (PMID 36293239, 2022). "Importantly, this result reminds us that the molecules responsive to glioma cell invasion might be regulated by NEDD4-1." (PMID 24340059, 2013). "Thus, we deduce that the effect of NEDD4-1 on glioma cell migration and invasion might be mediated by CNrasGEF." (PMID 24340059, 2013). "The observation that curcumin inhibited NEDD4-mediated signaling in SNB19 and A1207 glioma cells, thus interfering with cell motility, is very interesting." (PMID 34680593, 2021). "Then, we carried out RIP assays and found that LINC01198 directly binds NEDD4-1 and PTEN in glioma cells." (PMID 31469661, 2019).
glioma (continued). "NEDD4 is a E3-ubiquitin ligase involved in the degradation of CNrasGEFs, guanine nucleotide exchange factors (GEFs), that serve as RAS activators, thus, promoting glioma cell migration and invasion." (PMID 34680593, 2021). "Our results showed that LINC01198 could bind to both NEDD4-1 and PTEN, indicating that LINC01198 may function as a scaffold for NEDD4-1 and PTEN in glioma cells." (PMID 31469661, 2019). "A CCK-8 assay showed that forced LINC01198 expression neither increased cell proliferation nor promoted glioma cell resistance to temozolomide in NEDD4-1-knockout glioma cells." (PMID 31469661, 2019). "In addition, RNA pulldown assays further confirmed that LINC01198 indeed binds with NEDD4-1 and PTEN in glioma cells." (PMID 31469661, 2019). "The higher the grade of gliomas, the higher the level of NEDD4-1 expression (nontumorous=16.15±1.50%, low grade=40.32 ±4.01%, high grade=66.70± 5.44%, P<0.01, respectively)." (PMID 24340059, 2013). "But there is no report about the role of NEDD4-1 in cell invasive behavior, an important feature of gliomas." (PMID 24340059, 2013). "CNrasGEF was also located in cytoplasm and nuclei, but contrary to that of NEDD4-1, the number of CNrasGEF positive cells in glioma samples was significantly smaller than that in nontumorous brain tissues (P<0.01)." (PMID 24340059, 2013). "Although NEDD4-1 has been reported to promote proliferation of some cancer cells, there is no report about the role of NEDD4-1 in cell migration and aggressive behavior, one of important features of glioma." (PMID 24340059, 2013). "Analysis of the band densities revealed that in 41% of the glioma samples, the mRNA level of NEDD4-1 was approximately 2.8 fold higher than that of nontumorous tissues, but these samples had relatively normal CNrasGEF mRNA levels." (PMID 24340059, 2013). "Fourth, aberrant up-regulated NEDD4-1 showed reverse correlation with CNrasGEF protein level but not with its mRNA level in glioma tissues." (PMID 24340059, 2013). "To examine whether CNrasGEF mediated the effect of NEDD4-1 on cell migration and invasion, we co-tansfected NEDD4-1 and siCNrasGEF and tested the migration and invasion behavior of U251 glioma cells." (PMID 24340059, 2013). "However, in vitro experiments showed that overexpression or knockdown of LINC01198 did not affect NEDD4-1 expression in glioma cells." (PMID 31469661, 2019). "Moreover, overexpression or knockdown of LINC01198 did not affect PTEN expression in CRISPR/cas9-induced NEDD4-1-knockout glioma cells." (PMID 31469661, 2019). "Additionally, reduced LINC01198 expression neither inhibited cell proliferation nor increased glioma cell resistance to temozolomide in NEDD4-1 knockout glioma cells." (PMID 31469661, 2019). "Interestingly, aberrant up-regulated NEDD4-1 showed reverse correlation with CNrasGEF protein level but not with its mRNA level in glioma tissues." (PMID 24340059, 2013). "Furthermore, we assessed the expression and distribution of NEDD4-1 and CNrasGEF in nontumorous and glioma tissues by immunohistochemistry." (PMID 24340059, 2013). "Interestingly, the protein levels of CNrasGEF in these glioma tissues were lower than those of nontumorous tissues and there was an inverse correlation between NEDD4-1 and CNrasGEF protein levels (r= -0.79)." (PMID 24340059, 2013). "Strikingly, in many human glioma samples where the genetic background of CNrasGEF was normal but its protein levels were low, NEDD4-1 was highly expressed, suggesting that aberrant up-regulation of NEDD4-1 might post-translationally modify CNrasGEF in cancers." (PMID 24340059, 2013). "However, the result of western blotting showed that the protein levels of NEDD4-1 in 76% of glioma tissues were about 2.1 fold higher than those of nontumorous tissues." (PMID 24340059, 2013). "However, NEDD4-1 did not affect the proliferation and apoptosis of glioma cells." (PMID 24340059, 2013).
glioma (continued). "However, U251 and U87 glioma cells has mutated PTEN and our results showed that either overexpression or downregulation of NEDD4-1 could affect the migration and invasion of U251 and U87 glioma cells, suggesting that these effect of NEDD4-1 might not be mediated by PTEN." (PMID 24340059, 2013).
Hypertension (9 papers, 2015 to 2025). The presence of chronic increased pressure in the systemic arterial system. "Thus, the artificially genetic-engineered model of Nedd4-2 C2 loss revealed the underlying mechanism of salt sensitivity, which may account for resistant hypertension." (PMID 28604611, 2017). "Given that preeclampsia is a pregnancy-specific hypertensive disorder, the involvement of NEDD4L in hypertension suggests a potential link between NEDD4 and preeclampsia." (PMID 41220585, 2025). "Many of these proteins are involved in protein homeostasis and specifically in UPS, including proteasome α subunits, and NEDD4, an E3 ligase that increases in protein aggregates with aging and hypertension." (PMID 37092014, 2023).
multiple myeloma (8 papers, 2019 to 2025). "Low NEDD4-1 expression has been linked to poor prognosis in patients with multiple myeloma (MM), and NEDD4-1 knockdown results in bortezomib resistance in vitro and in vivo." (PMID 33935743, 2021). "In addition, the TCGA database shows that high expression of NEDD4 is associated with poor prognosis in patients with lung adenocarcinoma, multiple myeloma, and mesothelioma." (PMID 39890782, 2025). "In multiple myeloma cells, NEDD4 binds specifically to the Notch1 protein and increases its ubiquitination and degradation." (PMID 35355403, 2022). "mir-27 or Notch1 overexpression or NEDD4 silencing diminished autophagy but enhanced proliferation and invasion of multiple myeloma cells." (PMID 34769343, 2021). "Mir-27 negatively targets the ubiquitin ligase NEDD4, which specifically binds Notch1 to increase the ubiquitination of Notch1 in multiple myeloma cells." (PMID 34769343, 2021). "Collectively, mir-27 elevated Notch1 expression by targeting NEDD4 and promoted the development of multiple myeloma by inhibiting cell autophagy, thus providing a scientific basis for innovative treatment of multiple myeloma." (PMID 34769343, 2021). "Nonetheless, upregulation of NEDD4 resensitized multiple myeloma cells to bortezomib treatment via ubiquitination of Akt and degradation of pAkt-Ser473, while downregulation of NEDD4 resulted in bortezomib resistance in multiple myeloma cells." (PMID 35582023, 2021). "According to the Burington Myeloma Statistics, patients with recurrence exhibited lower NEDD4‐1 expression levels than those with primary occurrence." (PMID 31390487, 2020). "A recent study also suggested that low NEDD4 expression was closely related to worse outcomes in multiple myeloma." (PMID 31856858, 2019). "Using Mulligan Myeloma Statistics, we found that elevated NEDD4‐1 expression was a prognostic indicator for nonprogression and a Bor response in MM patients." (PMID 31390487, 2020).
non-small cell lung carcinoma (8 papers, 2017 to 2023). A group of at least three distinct histological types of lung cancer, including non-small cell squamous cell carcinoma, adenocarcinoma, and large cell carcinoma. "NEDD4 is highly expressed in 80% of non-small-cell lung carcinoma (NSCLC) tissues, as shown by immunohistochemical assays of tissue microarrays." (PMID 33288736, 2020). "Knockdown of NEDD4 significantly reduced EGF-stimulated cell migration in non-small cell lung carcinoma (NSCLC) cells." (PMID 29455656, 2018). "Inhibition of NEDD4 expression significantly suppressed proliferation of non-small cell lung carcinoma (NSCLC) cells and tumor growth in vivo." (PMID 28423617, 2017). "Similarly, NEDD4 has been implicated in the progression of non-small cell lung carcinoma (NSCLC)." (PMID 38097550, 2023). "In addition, overexpression of NEDD4 was also observed in non-small cell lung cancer and was shown to enhance drug resistance and tumor growth." (PMID 35031788, 2022). "A tissue microarray containing 103 non-small-cell lung carcinoma (NSCLC) resections revealed that NEDD4-1 is negatively correlated with PTEN protein, and the proliferation of NSCLC cells in vitro and in vivo was significantly inhibited due to the suppression of NEDD4-1 expression." (PMID 31787758, 2019).